SQSTM1 (sequestosome 1)
Diseases named in the same sentence as SQSTM1 in open-access papers (continued):
Sharing a sentence is not in itself a finding about the gene and the disease.
cancer (continued). "Given that SQSTM1-mediated mitophagy is required for preventing NDV-induced apoptosis and thus favors viral replication, it might explain why NDV preferentially replicates in cancer cells." (PMID 25051374, 2014). "However, to our surprise, in cancer cells overexpressing HA-tagged SQSTM1 plasmid without mRNA interference, PPI increased rather than decreased the levels of HA in neutral pH condition, while it was natural in low pH condition because PPI blocked autophagic flux." (PMID 29789637, 2018). "Excitingly, CUR5g also induced SQSTM1 and LC3B-II accumulation in other human cancer cells, but not in normal cells." (PMID 36316321, 2022). "P62/SQSTM1 stabilizes NRF2 in a non-canonical way by triggering Keap1 degradation, creating a positive feedback loop that sustains the antioxidant response that can help cancer cells survive stress." (PMID 36831129, 2023). "However, a very recent study has shown that VP demonstrate activity against cancer cell lines that is independent of YAP1 and instead dependent on the ability to induce high MW protein oligomers, in particular STAT3 and SQSTM1." (PMID 30263014, 2018).
infection (82 papers, 2012 to 2025). The state of being infected such as from the introduction of a foreign agent such as serum, vaccine, antigenic substance or organism. "HMGB1 and SQSTM1 are potential therapeutic targets for infection as well as sterile inflammation caused by tissue damage." (PMID 35769880, 2022). "A higher percentage of Salmonella was associated with endogenous LC3, NDP52, and SQSTM1 at 2 h post-infection in SACM1L KO cells than in WT cells, suggesting a delay in Salmonella-containing autophagosome maturation." (PMID 34320354, 2021). "We further showed that RGDV infection promoted the degradation of autophagic adapter SQSTM1 and caused the fusion of virus-containing autophagosomes with lysosomes." (PMID 29125860, 2017). "Among the interferon-stimulated proteins, two apoptosis-associated molecules (including NUB1 and STAT1) and two autophagy-associated proteins (including SQSTM1 and Irgm1) were significantly up-regulated only in the Hep-dG infection group." (PMID 26217322, 2015). "In IPEC-J2 cells, miR-215 mimic transfection during infection resulted in a significant reduction in genes coding for autophagy-related markers, including LC3B, SQSTM1 (sequestosome-1, p62) and lysosomal marker LAMP1 (Lysosomal-associated membrane protein 1)." (PMID 39943201, 2025). "We previously reported that the autophagy adaptor protein p62/SQSTM1, which directs substrates to autophagosomes, was degraded as early as 3 h post-infection in WT virus-infected cells, through an ICP0-dependent mechanism." (PMID 40990523, 2025). "Under conditions of cellular stress or infection, p62/SQSTM1 can bind to STING, facilitating its delivery to autophagosomes for degradation." (PMID 40165656, 2025). "The autophagy-related marker proteins LC3B, ATG5, and BECN1 were upregulated post-infection, whereas SQSTM1 was downregulated, indicating that FAdV-4 infection enhances autophagic flux and induces complete autophagy." (PMID 40130861, 2025). "Further to this, we show an accumulation of p62/SQSTM1, an accepted marker of autophagic flux, during the first 4 h of infection." (PMID 40042894, 2025). "The levels of intracellular LC3-II and SQSTM1 were significantly greater at 4–12 hpi in PRRSV-infected PAMs than in mock infection." (PMID 38940560, 2024). "The degradation of p62/SQSTM1 is recognized as an indicator of autophagic flux, and so we examined the expressions of p62/SQSTM1 by western blotting after ncp BVDV2 infection." (PMID 36533845, 2023). "We discovered a significant increase in the LC3-II expression as well as a statistically significant decrease in SQSTM1/p62 12 h after infection, indicating a complete autophagic flux." (PMID 37397000, 2023). "infection on cardiac autophagy, we evaluated the levels of SQSTM1/P62 and LC3-II, which indicate autophagic degradation." (PMID 37723152, 2023). "We then analyzed the impact of EV-D68 infection on autophagy markers in infected cells and observed that EVD-68, like PV, induces both gradual accumulation of LC3BII over the course of infection and cleavage of SQSTM1." (PMID 37819109, 2023). "On the other hand, in the NH4Cl group, the relative expression of MAP1LC3A, ULK2, and SQSTM1 was higher at early (6 to 14 hpe) and late time points (18 to 30 hpe) of the experimental infection in comparison with the artificial seawater group (p ≤ 0.05)." (PMID 35444958, 2022). "In our experiments, the rate of p62/SQSTM1 degradation, following the infection with TBEV and WNV, was similar." (PMID 36283999, 2022). "A more recent study on enterovirus D68 (EV-D68) found a similar cleavage based strategy to be common among picornaviruses by testing SQSTM1/p62 cleavage upon infection with EV-D68, poliovirus 1 (PV), rhinovirus 1A (RV1A) and CVB3 as a positive control." (PMID 34167456, 2021).
infection (continued). "Infection of macrophages with purified HIV-1 leads to a decrease in SQSTM1/p62, meaning that the autophagy flux is working during the first stages of the infection, and the lysosomal protease inhibitor pepstatin A reverts this situation." (PMID 33995324, 2021). "As intracellular bacteria are recognized, host xenophagy machinery, including ubiquitin, cargo receptors (NDP52 and SQSTM1), galectins (Gal3), and isolation membranes (marked by LC3), are recruited and associate with bacteria by 1 h post-infection." (PMID 34320354, 2021). "In HEK293 cells (human embryonal kidney) p62/SQSTM1 was similarly stable during the time course of infection." (PMID 34452452, 2021). "Acting as a viral restriction factor, p62/SQSTM1 restricts dengue virus replication during infection." (PMID 34900761, 2021). "Specifically, we observed changes in gene expression of key autophagy genes Atg5 and p62/SQSTM1 accompanying ZIKV-infection and replication in human primary placental trophoblasts when compared to mock-infected controls." (PMID 37431450, 2021). "Our study showed that the expression of autophagy-related genes ULK1, ATG13, ATG101, Beclin-1, ATG14, MAP1LC3A, and MAP1LC3B was significantly increased and that SQSTM1 was decreased in the muscle with pathogen infection." (PMID 33574492, 2021). "The ratio of LC3II/GAPDH showed an increasing trend by Western blotting, and the protein expression level of SQSTM1/p62 presented a similar trend after 4 h of infection." (PMID 32431700, 2020). "Infection with C. burnetii induces an increase in total and lipidated LC3 indicative of an induction of autophagy, although infection also results in an increase in SQSTM-1." (PMID 33251162, 2020). "For example, infection with several EVs, including CVB3, EV-D68, PV, and HRV1A, has been shown to cause the cleavage of SQSTM1/p62, suggesting a conserved EV strategy to subvert the host virophagy efforts." (PMID 30475087, 2019). "In contrast, later during infection, when polyubiquitin has accumulated on cytosolic bacteria, other cargo receptors, including SQSTM1/p62 and OPTN (optineurin), also contribute." (PMID 31258038, 2019). "Knockdown of SQSTM1 led to enhanced viral capsid protein (VP1) expression and increased cell-associated viral titers after 24 h infection with a low dose of CVB3 (multiplicities of infection (MOI) of 0.1)." (PMID 30154446, 2019). "Silencing of these genes also increased the accumulation of SQSTM1/p62 by impairing autophagic flux during EV-A71 infection." (PMID 28677644, 2017). "SQSTM1 expression decreased in infected cells during the early times of infection, corresponding to autophagy induction." (PMID 27509841, 2016). "TGEV-infected cells have lower levels of SQSTM1 protein at 12 h to 48 h post-infection, compared with mock-infected cells." (PMID 27027356, 2016). "Purified HIV induced a significant dose-dependent decrease in SQSTM1 protein levels corresponding to the stimulation of autophagic flux at 24 h post-infection." (PMID 26115100, 2015). "SQSTM1 protein levels became progressively greater from 3 d to 5 d post-infection and by 7 d post-infection were the same as the mock-infected controls (P > 0.05)." (PMID 26115100, 2015). "The accumulation of LC3-II and p62/SQSTM1 was observed with the employment of CQ at 24 h post-infection in BTV-infected cells compared with untreated controls, further indicating enhanced autophagic flux." (PMID 26287233, 2015). "Levels of p62/SQSTM1 were unaffected by WNV-NY infection at both early and late times post-infection." (PMID 23029249, 2012). "Interestingly, Ogawa and colleagues have also reported a hierarchical autophagic response in which LAPosomes undergo Sqstm1- and Optn-mediated xenophagy at later stages of infection." (PMID 40987772, 2025). "Above all, we speculate that the DnCPV-23 infection of host cells promotes autophagy and self-replication by upregulating SQSTM1 expression, which can be blocked by Baf A1." (PMID 40806613, 2025).
infection (continued). "In addition, we found that DnCPV-23 infection promoted the expression of Sequestosome 1 (SQSTM1/p62), an adaptor protein of selective autophagy, to promote the degradation of aggregate-prone proteins." (PMID 40806613, 2025). "Co-localization of p62/SQSTM1, ATG16, Rab5, Rab7a, and lysosomal-associated membrane protein 1 (LAMP1) with the LC3 protein were also observed, which confirmed that phagosome maturation occurs during infection including fusion with maturity or late endosomes." (PMID 35269494, 2022). "In fact, the results indicated that the SQSTM1 protein quantity was significantly higher in the NH4Cl group than the artificial seawater group during early (6 to 14 hpe) time points of the experimental infection (p ≤ 0.05)." (PMID 35444958, 2022). "The SQSTM1 protein quantity was found to be significantly higher in the virus+NH4Cl group than in the artificial seawater group at early (6 to 14 hpi) and late time points (18 to 30 hpi) of the experimental infection." (PMID 35444958, 2022). "Thus, many observations suggest a central role for P62/SQSTM1 upon infection with genotoxin- secreting bacteria in regulating DNA damage response." (PMID 33662035, 2021). "Additionally, in infected cells, we detected a strong colocalization of the virion signal with p62/SQSTM1 at the beginning of virion accumulation that was lost as the infection progressed." (PMID 34452452, 2021). "Notably, rapamycin was the only treatment to reduce the expression of p62/SQSTM1 compared with the infection-only group." (PMID 34900761, 2021). "At the same time, mRNA levels of Map1lc3b and Sqstm1 remained overall unchanged throughout the course of infection suggesting that increased P62 and LC3B-II levels were not caused by transcriptional upregulation, but rather accumulated by a SARS-CoV-2-induced blockage of autophagy." (PMID 34155207, 2021). "The infection of human lung fibroblast (MRC-5) cells with HCoV-OC43 initially results in higher levels of LC3-I expression that later translates into increased levels of LC3-II that correlate with an elevated number of SQSTM1 puncta." (PMID 34440791, 2021). "However, starvation during infection can still induce autophagic degradation as seen by a decrease in SQSTM-1." (PMID 33251162, 2020). "Degradation of SQSTM1/p62 was only observed in VV-infected A549 cells at 48 h post-infection." (PMID 31969562, 2020). "Around 18 hours post infection, the phagosome interacts with autophagosomes, thereby acquiring autophagy proteins such as microtubule-associated protein 1A/1B-light chain 3 (LC3) and sequestosome-1 (p62/SQSTM-1)." (PMID 31869379, 2019). "In addition, expression of the autophagic cargo receptor sequestasome (p62/SQSTM1) increased with time upon infection independently of GP63 and was sensitive to cycloheximide." (PMID 27280768, 2016). "Similarly, HIV infection induced a significant decrease in SQSTM1 protein levels (P < 0.001) corresponding to the stimulation of autophagic flux at 24 h post-infection." (PMID 26115100, 2015). "Of note, the autophagic adaptor SQSTM1, which is recruited to damaged mitochondria and is essential for their final clearance by autophagic degradation, was markedly decreased 2 d and almost disappeared 3 d after MV-Edm infection." (PMID 25004098, 2014). "Moreover, we found that HSP60 (a conservative mitochondrial protein) was markedly decreased following MV-Edm infection, however, it was massively preserved in SQSTM1 knockdown cells." (PMID 25004098, 2014). "Moreover, SQSTM1 expression started to decrease 48 h after MV-Edm infection, which was consistent with degradation of SQSTM1 via enhanced preserved autophagic flux." (PMID 25004098, 2014). "In human IAPA and CAPA patients, genes MAP1LC3B and SQSTM1, related to LAP were decreased, while CDC20, the gene encoding for the CDC20 protein which is involved in LC3 degradation, was upregulated in the superinfection group comparing to viral single infection." (PMID 36377895, 2022).
infection (continued). "However, kurarinone treatment induced the accumulation of p62/SQSTM1 protein in HCoV-OC43-infected cells starting at 6 h post-infection; p62/SQSTM1 protein-bound ubiquitinated protein is incorporated and degraded in the autophagosome, which indicates an autophagic degradation." (PMID 32674356, 2020). "Interestingly, the expression levels of autophagy-related proteins of LC3II (P < 0.01) and Atg5 were definitely increased (P < 0.001), while SQSTM1 were significantly decreased (P < 0.05) following the infection with ALV-J or the overexpression of GADD45β for 4 h in DF-1 cells or CEF cells." (PMID 32826872, 2020). "In addition, infection of cagA+/vacAs1m2 strains was significantly associated with increased levels of mRNA expression of SQSTM1, but not of BECN1." (PMID 28983474, 2017). "We postulate that SQSTM1 exhaustion might promote pro-apoptotic signaling and indeed, knockdown of SQSTM1 expression resulted in significant increase of apoptosis even at an early stage (2 d) after MV-Edm infection." (PMID 25004098, 2014). "In CSFV cell infection experiments, the high expression of autophagy markers ATG5 and BECN1 (Beclin 1), along with the degradation of SQSTM1 (Sequestosome 1), indicates that CSFV infection triggers a complete autophagy response." (PMID 40869159, 2025). "The retention of SQSTM1/p62 with LC3 was visible as early as 30 minutes and became firmly established after 8 hours of infection." (PMID 40395986, 2025). "ASFV particles colocalized with SQSTM1/p62 and LAMP2, indicating that ASFV virions entered the autolysosomes during the early phase of infection." (PMID 39688418, 2025). "In this study, infection of TFEB- and TFE3-knockdown cells with IBV, HCoV-OC43 and PEDV showed down-regulation of the pro-apoptotic factor CHOP and autophagy-related gene SQSTM1." (PMID 41450945, 2025). "We noticed that p72 interacts with SQSTM1/p62, and LC3-labeled autophagosomes colocalized with dot-like p72 in ASFV-infected PAMs, especially in the early phase of infection." (PMID 39688418, 2025). "We co-expressed TRIM21-HA and SQSTM1-FLAG in A549 cells and observed that DK/212 infection enhanced the interaction between TRIM21 and SQSTM1." (PMID 38542289, 2024). "Of note, infection by T. gondii significantly inhibited starvation-induced transcription of autophagy-related genes (i.e., ULK1, BECN1, PINK1, GABARAPL2, SQSTM1, and NBR1), as compared to uninfected serum-starved HFF cultures (i.e., “Control”)." (PMID 37387601, 2023). "In agreement, infection with TBEV and WNV decreased levels of p62/SQSTM1, which acts as a substrate during autophagic degradation." (PMID 36283999, 2022). "To further assess the effect of infection of human astrocytes with TBEV and WNV on autophagy, we immuno-labeled p62/SQSTM1 at 12, 24, and, 48 hpi." (PMID 36283999, 2022). "The results revealed that the relative expression of ULK2, SQSTM1, and MAP1LC3A was significantly higher in the virus group in comparison with the artificial seawater group at later time points of the experimental infection (18 to 30 hpi; p ≤ 0.05)." (PMID 35444958, 2022). "The SQSTM1 transcript was more rapidly and more intensively induced upon CCHFV infection and BECN1 expression was more rapidly augmented as well." (PMID 36298785, 2022). "Differential activation of autophagy and MTORC1 by SQSTM1/p62TRM, TBK1, TRAF6 and RALB, which are among the prominent molecules involved in both pathways, needs to be studied further in disease and/or infection-relevant settings." (PMID 32627660, 2021). "Infection with AdΔE4 allowed us to implicate a significant role for the E4 cassette in the degradation of the host factors DCAF1, RECQL4, SMARCA6, and SQSTM1." (PMID 34463575, 2021). "Autophagy played an antagonistic role in this infection model, as GFP-Sqstm1 (p62) also decorated a subset of bacteria and Sqstm1 knockdown impaired host survival." (PMID 35047422, 2021).